OPTN (optineurin)
Diseases named in the same sentence as OPTN in open-access papers (continued):
Sharing a sentence is not in itself a finding about the gene and the disease.
glioma (1 paper, 2025). A benign or malignant brain and spinal cord tumor that arises from glial cells (astrocytes, oligodendrocytes, ependymal cells). "This study is the first to identify TRIM16 as an upstream regulator of OPTN in glioma and to demonstrate that targeting this pathway can reverse TMZ resistance." (PMID 40990506, 2025).
intervertebral disc degeneration (1 paper, 2022). "Optineurin (OPTN) is a selective mitophagy receptor, and its role in intervertebral disc degeneration remains unclear." (PMID 36105191, 2022).
intracerebral hemorrhage (1 paper, 2025). A cerebrovascular disorder characterized by bleeding into one or both cerebral hemispheres including the basal ganglia and the cerebral cortex. "Studies have also found that Nrf2 interacts with the mitochondrial autophagy receptor optineurin (OPTN), regulating mitophagy to clear dysfunctional mitochondria following intracerebral hemorrhage (ICH)." (PMID 40083546, 2025).
ischemia (1 paper, 2025). A hypoperfusion of the BLOOD through an organ or tissue caused by a PATHOLOGIC CONSTRICTION or obstruction of its BLOOD VESSELS, or an absence of BLOOD CIRCULATION. "Under our experimental conditions, optineurin protein and mRNA levels were significantly reduced in the retina 24 h post-ischemia in vehicle-treated mice." (PMID 41285704, 2025).
juvenile open angle glaucoma (1 paper, 2024). Juvenile glaucoma (JG) is a rare autosomal dominant open angle glaucoma, characterized by early onset, severe elevation of intra ocular pressure of rapid progression, leading to optic nerve excavation and, when untreated, substantial visual impairment. "Mutations of OPTN have been widely considered a pathogenesis of POAG as well as NTG, of which E50K (c.148G>A) is the most common to be associated with POAG, and another mutation H486R (c.1457A>G) is correlated with juvenile open-angle glaucoma (JOAG)." (PMID 38674425, 2024).
lung adenocarcinoma (1 paper, 2018). A carcinoma that arises from the lung and is characterized by the presence of malignant glandular epithelial cells. "SUV39H2 could potentiate the tumorigenesis and invasion of lung adenocarcinoma cells, probably by repressing OPTN and STOM." (PMID 30348215, 2018).
lung squamous cell carcinoma (1 paper, 2025). "Our analysis revealed that high PINK1 mRNA levels in lung squamous cell carcinoma or OPTN in thyroid cancer are associated with improved survival." (PMID 39859167, 2025).
lymphoma (1 paper, 2023). A malignant (clonal) proliferation of B- lymphocytes or T- lymphocytes which involves the lymph nodes, bone marrow and/or extranodal sites.
nonalcoholic fatty liver disease (1 paper, 2023). "Furthermore, OPTN expression has been reported to be upregulated in patients with hepatocellular carcinoma and nonalcoholic fatty liver disease (NAFLD)." (PMID 37414782, 2023).
Obesity (1 paper, 2025). Accumulation of substantial excess body fat. "In the obesity signature, eight genes were found to possess regulatory functions: COPS5, GATA2, MORF4L1, OPTN, PFDN5, SETBP1, TCF4, and ZBTB16." (PMID 40102990, 2025).
pancreatic ductal adenocarcinoma (1 paper, 2020). An infiltrating adenocarcinoma that arises from the epithelial cells of the pancreas. "Furthermore, the silencing of OPTN in different cells lines of pancreatic ductal adenocarcinoma promotes cell cycle arrest, decreases colony formation and induces apoptosis through ER stress activation." (PMID 33634029, 2020). "These antecedents indicate OPTN could play a relevant role in pancreatic ductal adenocarcinoma cells." (PMID 33634029, 2020). "RNA-seq data of 17 different types of cancer show that OPTN is overexpressed in pancreatic cancer, being the second most expressed autophagy receptor, after p62, in this type of cancer, and its expression correlated with a reduced survival of pancreatic ductal adenocarcinoma patients." (PMID 33634029, 2020).
Primary glaucoma (1 paper, 2021). "Several genes have been demonstrated to be related with primary glaucoma, for example, optineurin (OPTN), myocilin (MYOC), optic atrophy 1, and neurotrophin 413–17." (PMID 34561506, 2021).
prostate adenocarcinoma (1 paper, 2025). "In prostate adenocarcinoma (PRAD), OPTN, PRKN, BNIP3L, PINK1, and MAP1LC3A were significantly downregulated." (PMID 39859167, 2025).
retinal diseases (1 paper, 2016). "The dysfunction of optineurin and TBK1 in retinal cells is assumed to play a significant role in glaucomatous and other retinal diseases by affecting the autophagy process and survival." (PMID 27454487, 2016).
urothelial carcinoma (1 paper, 2022). A malignant neoplasm derived from the transitional epithelium of the urinary tract (urinary bladder, ureter, urethra, or renal pelvis). "The expression of OPTN is down-regulated in urothelial carcinoma." (PMID 36419120, 2022).
ZIKV infection (1 paper, 2018). "The topological analysis on the extended network identified SH2B adaptor protein 3 (SH2B3), FGFR10P2, ACSL3, OPTN, SAMD8, and TNFRFS13B as additional key molecules associated with ZIKV infection." (PMID 30046058, 2018).
neurodegenerative disease (54 papers, 2010 to 2026). A disorder of the central nervous system characterized by gradual and progressive loss of neural tissue and neurologic function. "OPTN is implicated in several neurodegenerative diseases and plays essential roles in cellular processes such as autophagy, inflammatory regulation, and maintenance of cellular homeostasis." (PMID 41601638, 2026). "Our study provides new insights into the pathogenesis of NTG associated with OPTN (E50K) mutation, and a new perspective as a therapeutic and intervention target for this neurodegenerative disease associated with genetic factors." (PMID 35436991, 2022). "Necroptosis and RIPK1-mediated inflammation has been implicated in mediating neurodegenerative diseases such as ALS associated with specific mutations in TNFR1 pathway including OPTN and TBK158, 59, 62–65." (PMID 34376696, 2021). "Previous studies have shown that OPTN co-localizes with the major causative proteins related to neurodegenerative diseases such as HD, AD, and ALS, and OPTN has been considered to have critical roles in the pathogenic mechanisms of these conditions." (PMID 33065963, 2020). "Previous studies have shown that specific mutations in OPTN are associated with neurodegenerative diseases like glaucoma and ALS." (PMID 33065963, 2020). "Mutations in optineurin that cause defects in the interaction with TBK1 are associated with neurodegenerative diseases." (PMID 27620379, 2016). "These insights contribute to the understanding of microglial biology and may have relevance for neurodegenerative diseases in which optineurin and microglial dysfunction are implicated." (PMID 41226491, 2025). "In conclusion, our study suggests that gefitinib promotes PINK1/Parkin-mediated mitophagy via OPTN and may be beneficial for the treatment of neurodegenerative diseases that are associated with defective mitophagy." (PMID 38933121, 2022). "Importantly, these data imply that cell death is induced by optineurin mutations only in the appropriate, specific cell type associated with each different neurodegenerative disease." (PMID 29875767, 2018). "Dysfunction in autophagy and mitophagy is associated with a number of neurodegenerative diseases and so questions therefore remain as to how optineurin-mediated autophagy, and its dysfunction, plays a role in directing neuronal death pathways under specific stress conditions." (PMID 29867991, 2018). "Therefore, at least two aspects of functional property of OPTN are affected by the disease-causing E50K mutation, and both loss-of-function and gain-of-function mechanisms are likely involved in the pathogenesis of neurodegenerative diseases caused by this OPTN mutation." (PMID 27620379, 2016). "Mutations in OPTN have been identified as pathogenic factors in a variety of neurodegenerative diseases, including ALS, and mitophagy is specifically dependent on OPTN and its kinase TANK-binding kinase 1 (TBK1)." (PMID 40002740, 2025). "OPTN-mediated autophagy-dysfunction is closely related to a variety of diseases, such as Neurodegenerative diseases, Neurodegenerative diseases, Cancer, and Nephropathy." (PMID 38238458, 2024). "Consistently, gene mutations of autophagic receptors (e.g., SQSTM1 (sequestosome 1), OPTN (optineurin), NBR1 (neighbor of BRCA1 gene 1)) are closely associated with neurodegenerative diseases." (PMID 35845350, 2022). "We found that the expression of OPTN markedly decreased as IVDD was exacerbated, which is consistent with findings related to the expression of OPTN in degenerative diseases and the expression of other mitophagy-related genes in the intervertebral disc." (PMID 36105191, 2022). "Mutation of genes linked to autophagic processes—for example, SQSTM1, optineurin/OPTN, E3 ubiquitin ligase PARKIN/PRKN, PINK1, TBK1—have also been implicated in many neurodegenerative diseases." (PMID 34944054, 2021).
neurodegenerative disease (continued). "Mutations in autophagic receptors, such as p62 and optineurin (OPTN), are associated with a variety of neurodegenerative diseases, including PD, AD, and ALS." (PMID 33924878, 2021). "The relationship between astrocyte pathological activation and the regulation of receptors of optineurin and p62 is evident in different neurodegenerative diseases." (PMID 34638589, 2021). "One possible scenario in neurodegenerative diseases is that these binding partners interact aberrantly with mutant optineurin." (PMID 29875767, 2018). "Nevertheless, these data indicate that optineurin is part of the pathology of a wide range of neurodegenerative diseases, highlighting a central role for optineurin in protein aggregation." (PMID 29875767, 2018). "Together, our findings are valuable for understanding the functions of OPTN and TBK1 in selective autophagy, as well as the pathogenesis of neurodegenerative diseases caused by mutations of OPTN and TBK1." (PMID 27620379, 2016). "Optineurin foci are reminiscent of the inclusion bodies, Lewy bodies or aggresomes detected in neurodegenerative diseases." (PMID 24683533, 2014). "Taken together, our study highlights OPTN as a novel and important pharmacological target for manipulating mitophagy and suggests that activation of OPTN might be a new strategy to treat neurodegenerative diseases." (PMID 38933121, 2022). "The findings suggest that drugs regulating the optineurin signaling pathway may help treat bone degeneration and possibly other degenerative diseases." (PMID 33864025, 2021). "Likewise, intraneuronal aggregates of OPTN have been observed in other neurodegenerative diseases, including AD." (PMID 33685483, 2021). "Interestingly, optineurin is present and localized with in the aggregates in a wide range of neurodegenerative diseases." (PMID 29875767, 2018). "Mutations of optineurin and TBK1 are both associated with neurodegenerative diseases." (PMID 27620379, 2016). "Importantly, our structural data also provide mechanistic explanations to why several mutations found in OPTN and TBK1 can cause neurodegenerative diseases." (PMID 27620379, 2016). "Both OPTN and TBK1 mutants have TDP-43 proteinopathy, and the OPTN protein is incorporated into pathological aggregates present in several neurodegenerative diseases, including the DPR inclusions specific to C9ORF72-ALS/FTD." (PMID 35002606, 2021). "Similarly, mutations in non-kinase genes such as TARDBP, mHTT, and OPTN may also promote/reduce kinase activity by regulating abnormal protein expression, thereby unbalancing protein homeostasis and promoting the occurrence of neurodegenerative diseases." (PMID 40328798, 2025). "Future analyses of the interactomes of wild-type and mutant SQSTM1, TBK1 and VCP are needed to pinpoint how these proteins cooperate in a common complex with OPTN and UBQLN2 and how alterations in this complex may lead to ALS or other neurodegenerative diseases." (PMID 27164932, 2016).
tumor (33 papers, 2018 to 2025). "Recent studies have increasingly linked OPTN to both tumor-suppressive and oncogenic functions, demonstrating its dual role in cancer biology." (PMID 41294799, 2025). "Tumor-Suppressive Role of OPTN in Cancer: In other contexts, low OPTN expression is associated with increased tumorigenesis, highlighting its tumor-suppressive properties." (PMID 41294799, 2025). "Consequently, tumor progression is significantly reduced in OPTN-deficient HCC cells due to diminished mitophagy." (PMID 41294799, 2025). "As a negative regulator of GBM growth, OPTN suppresses tumor progression both in vitro and in vivo, with reduced OPTN levels being directly associated with increased GSC proliferation and self-renewal." (PMID 40002173, 2025). "One of the key mechanisms underlying OPTN’s tumor-suppressive role involves its interaction with HACE1, an E3 ubiquitin ligase that facilitates OPTN’s role in autophagic flux regulation." (PMID 41294799, 2025). "Onco-Stimulatory Role of OPTN in Cancer: In certain malignancies, overexpression of OPTN contributes to tumor growth and survival by enhancing autophagy and metabolic adaptation." (PMID 41294799, 2025). "OPTN protects against cancer immune evasion by playing a pivotal role in maintaining IFN-γ-mediated anti-tumor immune surveillance in CRC." (PMID 41294799, 2025). "More and more studies show that that HACE1 activates selective autophagy mediated by the HACE1-OPTN-P62 axis through ubiquitination of OPTN, thereby inhibiting tumor cell growth and progression." (PMID 40948788, 2025). "Overall, we noted a significant hypomethylation in tumor tissues for most genes in the signature, particularly of OPTN and SRC in KIRC, indicating potential epigenetic regulation." (PMID 39859167, 2025). "The role of OPTN in cancer is highly context-dependent, functioning either as a tumor suppressor or as an oncogenic driver." (PMID 41294799, 2025). "A previous study reported that the ubiquitination of the autophagy receptor OPTN (optineurin) by HACE1 activates selective autophagy for tumor suppression." (PMID 38660717, 2024). "As previously reported, HACE1 functions as a tumor suppressor by ubiquitinating OPTN and activating selective autophagy." (PMID 38660717, 2024). "In LUAD models, higher expression of OPTN in fibroblasts surrounding the tumor contributes to tumor invasiveness." (PMID 37628602, 2023). "For instance, it has been observed that OPTN induces pro-tumor mitochondrial-related autophagy, reducing the efficacy of combined treatments involving pemetrexed, cisplatin, and MEK inhibitors or anti-PD-L1 in a LUSC model." (PMID 37628602, 2023). "Similar to TLR9, understanding the function of OPTN allows us to differentiate its contribution to tumor growth based on its expression in surrounding cells." (PMID 37628602, 2023). "In terms of the application of OPTN in the context of mitophagy and the tumor environment, several studies have identified OPTN as a potential therapeutic target." (PMID 37628602, 2023). "Interfering with EEF1D gene expression in mice xenografted tumor significantly affected the levels of OPTN, p-Akt, Bcl-2, Bax, cleaved caspase-3 and ERCC1 compared to DDP treated mice alone, and had less effect on PI3K, Akt and caspase-3." (PMID 35672728, 2022). "Understanding the role of various components such as Pink1/Parkin, BNIP3, FUN14 domain-containing protein 1 (FUNDC1), optineurin (OPTN), microtubule-associated protein 1A/1B-light chain 3 (LC3), etc. in mitophagy will help in managing tumor progression." (PMID 36365094, 2022). "Here it is demonstrated that high OPTN expression was associated with worse prognosis of patients with HCC and that inhibition of OPTN expression suppressed tumor progression through impaired mitophagic activity in a mouse model of HCC and in an HCC cell." (PMID 33600074, 2021).